TAOK3 (TAO kinase 3)
Description:
Serine/threonine-protein kinase that acts as a regulator of the p38/MAPK14 stress-activated MAPK cascade and of the MAPK8/JNK cascade. In response to DNA damage, involved in the G2/M transition DNA damage checkpoint by activating the p38/MAPK14 stress-activated MAPK cascade, probably by mediating phosphorylation of upstream MAP2K3 and MAP2K6 kinases. Inhibits basal activity of the MAPK8/JNK cascade and diminishes its activation in response to epidermal growth factor (EGF). Positively regulates canonical T cell receptor (TCR) signaling by preventing early PTPN6/SHP1-mediated inactivation of LCK, ensuring sustained TCR signaling that is required for optimal activation and differentiation of T cells. Phosphorylates PTPN6/SHP1 on 'Thr-394', leading to its polyubiquitination and subsequent proteasomal degradation. Required for cell surface expression of metalloprotease ADAM10 on type 1 transitional B cells which is necessary for their NOTCH-mediated development into marginal zone B cells (By similarity). Also required for the NOTCH-mediated terminal differentiation of splenic conventional type 2 dendritic cells (By similarity). Positively regulates osteoblast differentiation by acting as an upstream activator of the JNK pathway. Promotes JNK signaling in hepatocytes and positively regulates hepatocyte lipid storage by inhibiting beta-oxidation and triacylglycerol secretion while enhancing lipid synthesis. Restricts age-associated inflammation by negatively regulating differentiation of macrophages and their production of pro-inflammatory cytokines (By similarity). Plays a role in negatively regulating the abundance of regulatory T cells in white adipose tissue (By similarity).
Synonyms: hKFC-A; DPK; JIK; MAP3K18
Tractability: Small molecule: a structure with a bound ligand is known; a high-quality ligand is known; it belongs to a druggable protein family. Antibody: UniProt places it where antibodies can reach, with high confidence; its Gene Ontology location is reachable by antibodies, with medium confidence. PROTAC: it is named in the literature on targeted protein degradation; ubiquitination databases record sites on it; its protein half-life has been measured; a small molecule that binds it is known.
Target class: STE protein kinase STE20 family; Enzyme; Kinase; STE protein kinase group; STE protein kinase TAO subfamily; Protein Kinase
Gene: Protein-coding gene on chromosome 12 (118,149,801 to 118,372,920, reverse strand). Ensembl gene ENSG00000135090.
Subcellular location: Cytoplasm; Cell membrane; Membrane raft; Lipid droplet
Subcellular location (Human Protein Atlas): Mitochondria
Pathways (Reactome):
Signal Transduction: RAC1 GTPase cycle; RAC2 GTPase cycle; RAC3 GTPase cycle
Gene Ontology:
Molecular function: protein binding; protein serine/threonine kinase activity; transferase activity; protein kinase inhibitor activity; ATP binding; protein kinase activity; protein serine kinase activity
Biological process: DNA damage response; MAPK cascade; mitotic G2 DNA damage checkpoint signaling; negative regulation of JNK cascade; positive regulation of JNK cascade; positive regulation of JUN kinase activity; positive regulation of stress-activated MAPK cascade; protein phosphorylation; neuron projection morphogenesis; regulation of MAPK cascade
Cellular component: cytoplasm; membrane raft; plasma membrane; lipid droplet
Genetic constraint (gnomAD): Loss-of-function variants: 21 observed, 89.09 expected, observed/expected ratio (o/e) 0.24, 90% interval 0.17 to 0.34. The upper end of that interval is the gene's LOEUF score, 0.34, which puts it in group 1 of 6, group 1 being the genes least tolerant of losing a copy. Missense variants: 642 observed, 950.41 expected, observed/expected ratio (o/e) 0.68, 90% interval 0.63 to 0.72. Synonymous variants: 293 observed, 335.88 expected, observed/expected ratio (o/e) 0.87, 90% interval 0.79 to 0.96.
Homologues: Orthologues: chimpanzee TAOK3 (99% identical), pig TAOK3 (98% identical), dog TAOK3 (98% identical), guinea pig TAOK3 (97% identical), macaque TAOK3 (97% identical), mouse Taok3 (96% identical), rat Taok3 (95% identical), tropical clawed frog taok3 (90% identical), zebrafish taok3a (83% identical), zebrafish taok3b (40% identical). Paralogues in human: TAOK1 (73% identical), TAOK2 (55% identical), SLK (27% identical), TNIK (25% identical), STK10 (24% identical), MAP4K4 (23% identical), MINK1 (23% identical), NRK (20% identical), MAP4K3 (20% identical), MAP4K5 (19% identical), MAP4K2 (18% identical), MAP4K1 (18% identical), and 23 more.
Diseases named in the same sentence as TAOK3 in open-access papers:
TAOK3 is named in the same sentence as 25 diseases in open-access papers, as found by Europe PMC text mining. Sharing a sentence is not in itself a finding about the gene and the disease. The quoted sentences say what the papers report.
breast carcinoma (3 papers, 2020 to 2026). "In this study, we screened paclitaxel response-associated kinases and provided evidence that TAOK3 overexpression reduced the sensitivity to anti-microtubule drug in breast cancer cells and was correlated with poor outcomes in patients." (PMID 33087151, 2020). "The thousand and one (TAO) kinases, TAOK1, TAOK2, and TAOK3, have garnered great interest for their role in, and therapeutic potential for, breast cancer, neurodegeneration in human tauopathies, and a large number of neurodevelopmental disorders (NDDs)." (PMID 41530942, 2026). "It has also been shown that reducing TAOK expression enhances the sensitivity to γ-radiation in colony survival assays, and knockdown of TAOK3 abolishes the drug resistance to microtubule-targeted drugs in breast cancer cells." (PMID 33050415, 2020). "We found the TAOK3 protein expression level was positive correlated to paclitaxel IC50 values in breast cancer cell lines." (PMID 33087151, 2020). "We also found that the expression of TAOK3 in breast cancer cell lines was generally higher than that in normal cells." (PMID 33087151, 2020). "Knock down of a top ranking gene, TAOK3, overcome taxane resistance in breast cancer both in vitro and in vivo." (PMID 33087151, 2020). "Ectopic downregulation of TAOK3 resulted in paclitaxel-resistant breast cancer cells sensitize to paclitaxel treatment in vitro and in vivo." (PMID 33087151, 2020). "The overexpression of TAOK3 conferred the sensitive breast cancer cells with an increased resistance to paclitaxel." (PMID 33087151, 2020). "Here we identified TAOK3 overexpression increased anti-microtubule drug resistance through upregulation of NF-κB signaling, which reduced cell death in breast cancer." (PMID 33087151, 2020). "In clinical microarray databases, high TAOK3 expressed breast cancer patients had poorer prognoses after adjuvant chemotherapy." (PMID 33087151, 2020). "In summary, we found that TAOK3 expression enhanced the paclitaxel resistance of breast cancer cells via the NF-κB signaling pathway." (PMID 33087151, 2020). "The expression of TAOK3 was positive correlative to the IC50 of paclitaxel in breast cancer cell lines." (PMID 33087151, 2020). "First, we determined the endogenous expression levels of TAOK3 in 12 breast cancer cell lines." (PMID 33087151, 2020). "TAOK3 to NF-κB signaling could be a new target for drug development and therapeutic strategies for breast cancer." (PMID 33087151, 2020). "Furthermore, clinical data were correlated with poor prognosis in breast cancer patients with high TAOK3 expression who accepted adjuvant therapy." (PMID 33087151, 2020). "Therefore, inhibition of the interaction between TAOK3 and NF-κB signaling may have therapeutic implications for breast cancer patients treated with anti-microtubule drugs." (PMID 33087151, 2020). "The expression of TAOK3 in normal breast epithelial cells (H184B5F5/M10 and MCF-10A) was significantly lower than in breast cancer cells." (PMID 33087151, 2020). "Downregulated TAOK3 expression in breast cancer cells enhanced the response to the drugs in non-silenced cells." (PMID 33087151, 2020).
liver steatosis (3 papers, 2021 to 2023). "To further examine the causative relationship between hepatic TAOK3 levels and liver steatosis, we characterized the effect of modifying the TAOK3 abundance on lipid metabolism in human hepatocytes." (PMID 34634521, 2021). "We also observed that TAOK3 expression in human liver biopsies is positively correlated with the severity of NAFLD assessed by hepatic steatosis, inflammation, and cellular damage scores, as well as liver fibrosis." (PMID 37864157, 2023). "To assess hepatic steatosis, we stained the liver sections from high-fat diet-fed Taok3–/– mice and wild-type littermates with the lipophilic dye Bodipy 493/503." (PMID 37864157, 2023). "Our study emphasizes the importance of lipid droplet-binding proteins in the control of intrahepatocellular fat storage and highlights the inhibition of lipid droplet decorating STE20-type kinase TAOK3 as a potential NAFLD therapy via antagonizing hepatic steatosis." (PMID 34634521, 2021). "Our earlier investigations have revealed that TAOK3 transcript levels in human liver biopsies are positively correlated with the key lesions of NAFLD [i.e., hepatic steatosis, inflammation, and ballooning;]." (PMID 37864157, 2023). "We found a positive correlation between the TAOK3 levels and all three individual components of the NAS (i.e., liver steatosis, lobular inflammation, and hepatocellular ballooning) as well as total NAS." (PMID 34634521, 2021). "We found that the TAOK3 transcript levels in human liver biopsies were positively correlated with the key lesions of NAFLD (i.e., hepatic steatosis, inflammation, and ballooning)." (PMID 34634521, 2021).
Obesity (2 papers, 2022 to 2023). Accumulation of substantial excess body fat. "Importantly, to date, no studies have described the in vivo impact of TAOK3 on hepatic lipid storage or insulin sensitivity in connection to obesity." (PMID 37864157, 2023). "Together, our results demonstrate that genetic deficiency of TAOK3 in mice failed to mitigate the development of diet-induced NAFLD and had no impact on the progression of systemic glucose intolerance or insulin resistance in the context of obesity." (PMID 37864157, 2023). "The aim of this study was to examine the in vivo role of STE20-type protein kinase TAOK3, which has been previously reported to regulate hepatocellular lipotoxicity in vitro, in the development of NAFLD and systemic insulin resistance in the context of obesity." (PMID 37864157, 2023).
steatosis (2 papers, 2021 to 2023). Increased lipid within the cytoplasm of cells. "Despite a critical role of TAOK3 in the regulation of lipid storage and oxidative/ER stress described previously in vitro in cultured human hepatocytes, we found no alterations in steatosis or associated lipotoxic damage in the livers from Taok3 knockout mice vs. wild-type controls." (PMID 37864157, 2023). "Notably, subjects with NAS ≥5, which defines definite NASH (n = 24), had a 1.8 ± 0.2-fold increase in the TAOK3 expression compared with subjects with NAS ≤4, which indicates simple steatosis or borderline NASH (n = 38; P = 0.008)." (PMID 34634521, 2021).
esophageal squamous cell carcinoma (1 paper, 2023). Esophageal squamous cell carcinoma (ESCC) is a type of esophageal carcinoma (EC) that can affect any part of the esophagus, but is usually located in the upper or middle third. "TAOK3 can augment autophagy and chemo‐resistance in esophageal squamous cell carcinoma (ESCC) cells mechanically by phosphorylating KMT2C and promoting the interaction between KMT2C and ETV5." (PMID 37705061, 2023).
Ewing sarcoma (1 paper, 2012). A small round cell tumor that lacks morphologic, immunohistochemical, and electron microscopic evidence of neuroectodermal differentiation. "The first module includes STK10, TNK2 and TAOK3, which were identified to be significant across all four Ewing's sarcoma cell lines." (PMID 22761558, 2012).
hepatocellular carcinoma (1 paper, 2018). A malignant tumor that arises from hepatocytes. "TAOK3 is also involved in hepatocellular carcinoma and has been shown to be an androgen-responsive gene." (PMID 29643985, 2018).
liver fibrosis (1 paper, 2023). "Furthermore, no alterations in hepatic fibrosis were found in Taok3 knockout mice as demonstrated by comparable labeling for liver collagen IV and Picrosirius Red (stains collagen I and III) in both genotypes." (PMID 37864157, 2023).
pancreatic cancer (1 paper, 2020). "In addition, a previously identified ITK inhibitor (NCGC00188382) was shown to inhibit the activity of TAOK3, aurora B kinase, and cyclin-dependent kinase 7 in pancreatic cancer cells and suppress the stemness traits and growth of tumor spheroids." (PMID 33050415, 2020). "In this study, the authors identified an ITK inhibitor, NCGC00188382, which could inhibit the activity of TAOK3, aurora B kinase, and cyclin-dependent kinase 7 in cancer cells and suppress the stemness traits and growth of pancreatic tumors." (PMID 33050415, 2020).
peritonitis (1 paper, 2023). Inflammation of the peritoneum (tissue that lines the abdominal wall and covers most of the organs in the abdomen). "However, the induction of acute peritonitis in Taok3 deficient mice significantly increased the proportion of CD11b + cells compared to wild type." (PMID 37400834, 2023). "It implies that most of the cells that populated the peritoneal cavity of Taok3−/− mice after the induction of peritonitis migrated from the periphery." (PMID 37400834, 2023).
schizophrenia (1 paper, 2021). A major psychotic disorder characterized by abnormalities in the perception or expression of reality. "A study with a rare CNVs analysis by WGS suggested that a de novo deletion that affects TAOK3 (and PEBP1) may contribute to schizophrenia and TAOK3 (but not PEBP1) was further confirmed in a GWAS analysis, suggesting LOF of monogenic TAOK3 may contribute to NDDs, at least in schizophrenia." (PMID 33867937, 2021).
cancer (8 papers, 2018 to 2023). A tumor composed of atypical neoplastic, often pleomorphic cells that invade other tissues. "Three clear examples are Cd44, Celf2, and Taok3 which are overall highly expressed in the process and related to cell adhesion or cancer progression." (PMID 36329018, 2022). "The overexpression of TAOK3 has been shown to activate known cancer pathways that regulate cell survival, growth and differentiation." (PMID 29643985, 2018). "A demonstrated relationship between NF-κB mediated signaling and TAOK3 could also imply the presence of inflammatory responses in cancer cells." (PMID 37400834, 2023). "Furthermore, by analyzing the correlation of clinicopathologic parameters with TAOK3 level in ESCC tissues, we found that TAOK3 protein level was higher in stage III+IV cancers than in stage I+II cancers and positively associated with tumor stage." (PMID 37705061, 2023). "In the future, TAOK3 as a molecular target in cancer treatment should be evaluated." (PMID 33087151, 2020). "TAOK3 overexpression activates mitogen-activated protein kinases (MAPK), a known cancer signaling pathway, via ERK1/ERK2, JNK/SAPK and p38." (PMID 29643985, 2018). "From TCGA analysis and qPCR, and western blot in ESCC tissues collected from five enrolled patients, we found that of these three TAO kinases, TAOK3 was confirmed to be overexpressed in ESCC, and its expression level in ESCC ranked high among all kinds of cancers." (PMID 37705061, 2023). "Previous studies have shown that TAOK3 and ABCC1 are involved in various cancers." (PMID 29643985, 2018).
tumor (6 papers, 2020 to 2024). "Meanwhile, Stratification analysis uncovered that TAOK3 protein expression in ESCC tissues was positively associated with tumor size (P = 0.042), metastasis (P = 0.002), and TNM stage (P<0.001)." (PMID 37705061, 2023). "The role of TAOK3 has also been implicated in tumor initiation and metastasis formation in pancreatic cancer and reduced cell death in breast cancer." (PMID 34634521, 2021). "For instance, fusions of oncogenic proteins TAZ, YAP1, and HIPK2 preserve their tumor-promoting function, while fusions of tumor suppressors, such as NF2, LATS1, FAT1, PTPN14, DCHS2, TAOK1, and TAOK3, results in loss of their function." (PMID 38499647, 2024). "To access the effect of paclitaxel treatment on different TAOK3 expression levels in vivo, we determined the paclitaxel response effects in Hcc1806 and Hs578T using an in vivo subcutaneous xenograft tumor model." (PMID 33087151, 2020). "After the tumor metastasis assay was performed, we found TAOK3 or ETV5 or IRGM knockdown could robustly reduce the average number of lung metastasis nodules and the size of metastasis nodules indicated by HE staining." (PMID 37705061, 2023). "However, we corroborated the tumor-suppressive roles of insertions in Adk and Zbtb20 and in Nipbl, Pdlim5, Ppp1r12a, Tnrc6b, Brd4, Cul3, Ctnna3, Elavl1, Gphn, Nfia, Ptpn12, Taok3, and Rasa1." (PMID 33435458, 2021). "Interestingly, the microarray data analysis of the large cohort of HCC patients available at the GEO database (n = 214) demonstrated that the TAOK3 gene expression was significantly higher in HCC tumors than in the adjacent non-tumor liver tissue (P < 0.0001; GSE14520)." (PMID 34634521, 2021). "To evaluate the effects of TAOK3 inhibitor SBI‐581 in vivo, we further performed the tumor growth assay, and found the tumor growth was alleviated when mice were treated with SBI‐581 and cisplatin respectively." (PMID 37705061, 2023). "Collectively, these data imply that under the effect of TAOK3's phosphorylation, KMT2C mediates histone methylation and transcriptionally upregulates the expression of IRGM together with ETV5, and tumor autophagy is augmented consequently." (PMID 37705061, 2023). "TAOK3 protein abundance was also enhanced in frequently used human HCC cell lines (poorly differentiated SNU-475 and well-differentiated Hep3B) versus non-tumor IHHs." (PMID 34634521, 2021). "Results showed that this agent inhibited TAOK3, CDK7 and aurora B kinases and that TAOK3 signaling is required for tumor initiation and metastasis formation." (PMID 33198323, 2020). "Considering that TAOK3 promotes ESCC progression in this study dependent on its kinase activity, we look forward to seeking out specific inhibitor for TAOK3 in order to find a way to ameliorate their effects on tumor progression." (PMID 37705061, 2023). "In addition, we also found that the necrosis area was decreased when tumor with TAOK3 overexpression but without paclitaxel treatment." (PMID 33087151, 2020).
cardiovascular disease (1 paper, 2022). "At the same time, the peptide also regulated the expression of the Efna4 and Taok3 genes in the MAPK signaling pathway, which has important functions in cardiovascular disease, can repair vascular injury, and is involved in cardiac remodeling." (PMID 35479750, 2022).
TAOK3 also shares sentences with these, for which no sentence is quoted: prostate carcinoma (3 papers); acute myeloid leukemia (1); bipolar disorder (1); cervical carcinoma (1); chronic pancreatitis (1); fungal infection (1); Glucose intolerance (1); Insulin resistance (1); melanoma (1); neurodevelopmental disorder (1); tauopathies (1).